OCLN (occludin)
Diseases named in the same sentence as OCLN in open-access papers (continued):
Sharing a sentence is not in itself a finding about the gene and the disease.
breast carcinoma (39 papers, 2006 to 2025). "Visualization of the gene interaction network of cathepsin S revealed the degradation of occludin, which would result in the metastasis of cancer cells causing bone and breast cancers." (PMID 34827106, 2021). "Loss of occludin causes increased cell invasion, reduced adhesion, and impaired tight junction integrity in breast cancer tissues." (PMID 28288645, 2017). "Slight association between reduced OCLN expression and poor overall survival was observed in a cohort with 10-year follow-up of breast cancer patients, and studies conducted on human cell lines demonstrated that OCLN phosphorylation by SRC attenuates its assembly at the tight junctions." (PMID 33450402, 2020). "Also, we found weak expression of OCLN and strong expression of TGFβ2, an association which was previously demonstrated to be linked to the breast cancer epithelial mesenchymal transition (EMT)." (PMID 21858074, 2011). "Indeed, in human breast cancer, tumour tissues show truncated and/or variant signals for occludin." (PMID 22559840, 2012). "The claudin-low group of breast cancers presents, as a defining characteristic, the down-regulation of the expression of adhesion proteins such as claudins 3, 4 and 7, occludin and E cadherin." (PMID 37504297, 2023). "Downregulation of OCLN has been observed in clear cell renal cell carcinoma, hepatocellular carcinoma, breast cancer, endometrial cancer, and lung cancer." (PMID 37658903, 2023). "A study confirmed that the gut barrier of breast cancer patients was severely damaged and the expression levels of the tight junction proteins ZO-1 and occludin were significantly decreased." (PMID 36093113, 2022). "Another group also reported that EVs containing miR-105 released from metastatic breast cancer cells destroyed the vascular endothelial barrier by inhibiting the expression of tight junction proteins, zonula occludens-1, occludin, and VE-cadherin." (PMID 36057626, 2022). "Down-regulation of the occludin has been reported in gastric cancer, hepatocellular carcinoma and breast cancer." (PMID 31754355, 2019). "Animal studies revealed that knock-down of occludin in the breast cancer cells leads to the increased invasiveness." (PMID 31754355, 2019). "Further, occludin induces premature senescence in breast cancer cells, which can be blocked by chemical inhibition of the mitogen-activated protein kinase (MEK) pathway." (PMID 31783547, 2019). "In another study, functional regions of occludin in human tissues and breast cancer cell lines were amplified." (PMID 27547510, 2016). "Western blot analyses indicated that TMEM88 promoted Snail expression and inhibited Zo-1 and Occludin expression by interacting with dishevelled (Dvl) proteins, thereby stimulating invasion and metastasis in breast cancer." (PMID 26325443, 2015). "As expected, epithelial genes known to be inactivated during EMT in breast cancer cells, such as Cdh1 (E-cadherin), Ocln (Occludin), Epcam, Cldn7 (Claudin 7), Id1, Krt7, Esr1, Cav2, Dsp, Gata3, and Cadm1 were among the downregulated genes." (PMID 25674539, 2015). "A relationship between reduced occludin expression and unfavorable tumor phenotype or poor prognosis has earlier been reported for carcinomas of the breast, gallbladder, gastrointestinal tract, endometrial cancer as well as squamous cell carcinomas of the esophagus." (PMID 40173205, 2025). "Fucoidan intake has been found to restore the microbiota and intestinal barrier function by regulating tight junction-associated proteins (ZO-1, occludin, claudin-1, and claudin-8) and the MAPK signaling pathway in a 7,12-dimethylbenz[a]anthracene (DMBA)-induced breast cancer rat model." (PMID 35719088, 2022). "Then, we analyzed by western blotting the expression of EMT markers which showed a decrease in the expression of epithelial markers (E-cadherin and occludin) and an increased expression of mesenchymal markers (vimentin and N-cadherin) in Elovl5-silenced breast cancer cells." (PMID 36056008, 2022).
breast carcinoma (continued). "Also, the inactivation of CXCL12 stabilized endothelial tight junction expression like TJP-1 and occludin in breast cancer metastasis." (PMID 32210974, 2020). "Similarly, stable occludin expression in melanoma and breast cancer cells followed by injection into the craniolateral thorax and mammary fat pad, respectively, reduced the size of lung metastases." (PMID 31783547, 2019). "This loss of or aberrant expression has clear repercussions as to the importance of occludin in maintaining TJ integrity in breast tissues and could play a part in breast cancer development." (PMID 22559840, 2012). "Moreover, expression of occludin in the human breast cancer cell lines tested also varied." (PMID 27547510, 2016). "Upregulated of E-cadherin and Occludin, but decreased levels of N-cadherin, Vimentin, and Snail expression were detected in the breast cancer cell lines upon VEGF or NRP1 silencing in the breast cancer cells." (PMID 40277760, 2025). "In support of a link between ARIH1 expression and EMT induction, analysis of human breast cancer proteome data revealed an inverse correlation between ARIH1 protein levels and levels of the epithelial markers E-cadherin and Occludin." (PMID 35102251, 2022). "We detected a significant increase in occludin and BCA-1 mRNA levels in cells treated with sera of breast cancer patients with cerebral metastases compared to cells treated with the control serum." (PMID 32321535, 2020). "The experiments further demonstrated that SPG-56 inhibited the metastasis of breast cancer in MCF-7 and 4T1-bearing mice by altering the expression of MMP2, MMP9, VEGF, Occludin and Claudin." (PMID 30651572, 2019). "Conversely, Hsp90AA1 overexpression upregulated vimentin and downregulated E-cadherin and occludin, suggesting that Hsp90 plays a vital role in EMT in breast cancer." (PMID 31921692, 2019). "The level of occludin immunostaining was unrelated to parameters of tumor aggressiveness in breast cancers of no special type, gastric, endometrial and thyroidal cancer." (PMID 40173205, 2025). "Breast cancer with the bone metastasis showed significantly lower occludin expression in comparison with those without bone metastasis." (PMID 31754355, 2019). "These were Estrogen Biosynthesis (HSD17B7 and HSD17B12), Estrogen-Dependent Breast Cancer Signaling (HSD17B7 and HSD17B12), Hepatic Fibrosis/Hepatic Stellate Activation (CD14 and CD40), Tight Junction Signaling (CDSF1 and OCLN), and Dopamine-DARPP32 Feedback in cAMP Signaling (CACNAID and CSNK1E)." (PMID 23759029, 2013). "Recently, a report demonstrated that inhibition of MEK1 signaling did not influence expression of occludin or claudin-1 or affect tight junction function in several breast cancer cell lines." (PMID 16504032, 2006). "Similarly, immunostainings of the tumors against antibodies for CD31, VEGF, and OCCLUDIN showed that Prox1 reduced all three markers, indicating a decrease in angiogenesis as well as in the EMT capacity of the breast cancer tumors." (PMID 37508533, 2023). "Furthermore, the less pronounced effects of MCF7CM on Occludin compared to Claudin-5 mRNA expression suggest that breast cancer cells target the Claudin-5 TJs pathways rather than Occludin." (PMID 34943153, 2021).
endotoxemia (39 papers, 2013 to 2025). "On the other hand, alterations in tight junction (TJ) proteins such as ZO-1, occludin, and claudin have been linked to increased intestinal permeability and systemic endotoxemia." (PMID 40964057, 2025). "In the present study, the decreased occludin and claudin-1 expression in the intestinal mucosa was associated with systemic endotoxemia." (PMID 38255265, 2024). "LPS in the blood can cause endotoxemia, and the tight junction composed of transmembrane proteins, such as Occludin and Claudin-1, is disrupted, resulting in increased intestinal permeability and subsequent liver inflammation." (PMID 38892467, 2024). "Our previous study confirmed that Fn041 directly regulates the mRNA expression of several tight junction genes, such as Zo1, occludin, and claudin-6, to prevent barrier damage and endotoxemia caused by a high-fat diet." (PMID 35369106, 2022). "The significant inverted correlation of occludin and claudin-1 expression with serum endotoxin concentration points towards a causal relationship between the disruption of enterocyte TJs and systemic endotoxemia in CKD." (PMID 38397970, 2024). "Previously, it was reported that T2DM and dysbiosis of gut microbiota led to impaired intestinal permeability, increased LPS levels and caused endotoxemia and metabolic disorders, which eventually affected the expression of colon tight junction proteins (ZO-1, occludin, and claudin-1)." (PMID 36276816, 2022). "Previous studies reported that patients with metabolic diseases such as those with T2DM or obesity display low-grade endotoxemia consequent to changes of proteins implicated in intestinal epithelial cell permeability, such as the tight junction (TJ) proteins ZO-1 or occludin." (PMID 35631294, 2022). "Heart failure, regardless of the type of ejection fraction, results in a significant decrease in enterocytic occludin and claudin-1 expression, which may represent an important cellular mechanism for the intestinal barrier dysfunction causing systemic endotoxemia and inflammatory response." (PMID 38255265, 2024). "Our study showed an inverse correlation between intestinal occludin and claudin-1 expression and the extent of systemic endotoxemia." (PMID 38255265, 2024). "Intestinal occludin and claudin-1 were significantly decreased, and their expression was inversely correlated with systemic endotoxemia." (PMID 38397970, 2024). "Occludin and claudin-1 expression inversely correlated with systemic endotoxemia (p < 0.05 and p < 0.01, respectively)." (PMID 38255265, 2024). "By contrast, ITF only significantly increase colonic occludin expression, but was unable to change endotoxemia." (PMID 37615336, 2023). "Our results confirmed that endotoxemia induced severe colonic tight junction barrier dysfunction with lower expression of occludin and ZO1." (PMID 33679744, 2021). "Our results show that EtOH-treated mice had reductions in mRNA and protein expression of intestinal tight junction proteins, including claudin one and occludin, and increases in intestinal permeability and endotoxemia compared to pair-fed mice." (PMID 33815111, 2021). "The mucins Mucin-2 and Mucin-3, as well as occludin and ZO-1, are systematically involved in various enteral and parenteral diseases via endotoxemia regulation." (PMID 34681423, 2021). "Isoorientin (25 and 50 mg/kg) and LiCl (100 mg/kg) upregulated the expression of occludin, ZO-1 and p-GSK3β in the brain of endotoxemia mice, showing a good potential of reversing the destruction of BBB and treatment for GSK3β-related brain diseases." (PMID 33192176, 2020). "By exploiting biochemical, immunocytochemical, immunohistochemical, and functional approaches, we demonstrate that OX-A preserves the IEB and occludin expression, thus preventing endotoxemia and subsequent neuroinflammation." (PMID 31024456, 2019).
endotoxemia (continued). "We then further examined the influence of curcumin on intestinal tight junction proteins expression such as occludin and zonula occluden-1, which are consistent with gut barrier dysfunction contributing to endotoxemia during NAFLD." (PMID 31788011, 2019). "VOA and BA improved the intestinal mucosal barrier by increasing the expression of ZO-1 and occludin protein and blocking endotoxin translocation-induced endotoxemia." (PMID 29170638, 2017). "GLP-2 elicits improvements in gut permeability and endotoxemia and increases expression of zonula occludens-1 (ZO-1) and occludin." (PMID 27437400, 2016). "Our animal experiment showed that external administration of IGF-1 reduced endotoxemia in liver cirrhotic rats via up-regulating occludin and claudin-1 expression in intestines." (PMID 26152281, 2015). "In general, TSG was found to improve the function of intestinal mucosal barrier, increase the expression of the ZO-1 and occludin protein, and inhibit endotoxin-translocation-induced endotoxemia." (PMID 26474417, 2015). "It resulted in the reduction of endotoxemia (through LPSs) and pro-inflammatory cytokine (TNF-α, IL-6, and IL-1β) levels, with the increased expression of tight-junction associated proteins (claudin-1, occludin, and zonula occludens-1)." (PMID 41334341, 2025). "The combined administration of SGP and PTX could improve intestinal barrier function by suppressing endotoxemia and upregulating tight junction proteins, such as E-cadherin, β-catenin, occludin and ZO-1." (PMID 35865946, 2022). "In the restraint stress rotenone-induced was observed analogous changes as in the rotenone alone group with several exceptions; intestinal hyperpermeability, an abnormal expression of Occludin and Claudin1, and increased ratio of fecal Akkermania and endotoxemia." (PMID 34691361, 2021). "Moreover, the oral administration of P. gingivalis in mice was also found to significantly exacerbate endotoxemia while reducing the transcription of genes such as ZO-1, occludin and Tjp1 tight junction proteins in the small intestine." (PMID 34064692, 2021). "Isoorientin increased the expressions of occludin and ZO-1 in the brain of endotoxemia mice." (PMID 33192176, 2020). "We further found that the intestinal tight junction proteins (occludin and ZO-1) were increased by β-glucan supplementation along with reduced systemic endotoxemia indicating increased integrity of the epithelial barrier and reduction of translocation of bacterial LPS into the circulation." (PMID 33008466, 2020). "The occludin and ZO-1 decreased in the cortices of endotoxemia mice compared to the control, while isoorientin (25 and 50 mg/kg) and LiCl (100 mg/kg) increased the expressions of occludin and ZO-1 in endotoxemia mice, which meant preventive effects of isoorientin on the disruption of BBB." (PMID 33192176, 2020). "In general, VOAV could protect the function of intestinal mucosal barrier, increase the expression of the occludin and ZO-1 proteins, and ameliorate endotoxin translocation induced endotoxemia." (PMID 30112382, 2018). "Studies have found that endotoxemia decreases pulmonary epithelial barrier function, activates NF-κB in lung tissue, increases pulmonary iNOS expression and decreases the expression of the TJ proteins occludin and ZO-1." (PMID 24884662, 2014). "The deterioration of TJ proteins such as occludin and JAM-A have also been shown to upset barrier functions, leading to leaky-gut and endotoxemia." (PMID 36767519, 2023). "Especially, JQ1 further rescued the missing expression of tight junction proteins occludin and ZO1, and obviously reversed the colon integrity in endotoxemia." (PMID 33679744, 2021). "Lower protein levels of occludin and ZO1 in endotoxemia colons compared to the saline-treated control were detected by western blot." (PMID 33679744, 2021).
endotoxemia (continued). "Isoorientin inhibited inflammatory responses in endotoxemia mice, increased p-GSK3β (Ser9), and protected the integrity of BBB by increasing the tight junction protein occludin and ZO-1 in the brain." (PMID 33192176, 2020). "Recently, researchers have proposed that high levels of endotoxemia are related to gut permeability and decreased tight junction protein expression such as ZO1 and occludin." (PMID 29899272, 2018). "The aim of this study was to investigate whether the expression of the key TJ proteins occludin and claudin-1 is altered in the intestinal mucosa of patients with stage I–IV CKD or ESKD, contributing to systemic endotoxemia and inflammatory responses." (PMID 38397970, 2024). "Here, through evaluating the mucous morphology and the expression of tight junction proteins such as occludin and ZO1, we found the upregulation of BRD4 in damaged colon with poor tight junction in an endotoxemia mouse model induced by lipopolysaccharides (LPS)." (PMID 33679744, 2021). "Moreover, downregulated tight junction proteins occludin and ZO1 were also detected to further verify the colon barrier damage in endotoxemia." (PMID 33679744, 2021).